CAVIN1 (caveolae associated protein 1)
Description:
Plays an important role in caveolae formation and organization. Essential for the formation of caveolae in all tissues. Core component of the CAVIN complex which is essential for recruitment of the complex to the caveolae in presence of calveolin-1 (CAV1). Essential for normal oligomerization of CAV1. Promotes ribosomal transcriptional activity in response to metabolic challenges in the adipocytes and plays an important role in the formation of the ribosomal transcriptional loop. Dissociates transcription complexes paused by DNA-bound TTF1, thereby releasing both RNA polymerase I and pre-RNA from the template (By similarity). The caveolae biogenesis pathway is required for the secretion of proteins such as GASK1A (By similarity).
Synonyms: PTRF; FKSG13; cavin-1; CGL4; CAVIN
Tractability: Antibody: UniProt places it where antibodies can reach, with high confidence; its Gene Ontology location is reachable by antibodies, with high confidence; the Human Protein Atlas places it where antibodies can reach. PROTAC: UniProt records ubiquitination sites on it; ubiquitination databases record sites on it.
Gene: Protein-coding gene on chromosome 17 (42,402,449 to 42,423,256, reverse strand). Ensembl gene ENSG00000177469.
Subcellular location: Membrane, caveola; Cell membrane; Microsome; Endoplasmic reticulum; Cytoplasm, cytosol; Mitochondrion; Nucleus
Subcellular location (Human Protein Atlas): Plasma membrane; Vesicles
Pathways (Reactome):
Signal Transduction: RHOA GTPase cycle; RHOB GTPase cycle; RHOC GTPase cycle
Gene expression (Transcription): RNA Polymerase I Transcription Termination
Gene Ontology:
Molecular function: identical protein binding; protein binding; RNA binding; rRNA primary transcript binding
Biological process: termination of RNA polymerase I transcription; transcription initiation at RNA polymerase I promoter; positive regulation of cell motility; rRNA transcription; protein secretion
Cellular component: caveola; cytoplasm; membrane raft; mitochondrion; nucleus; plasma membrane; protein-containing complex; nucleoplasm; cytosol; endoplasmic reticulum
Genetic constraint (gnomAD): Loss-of-function variants: 16 observed, 22.25 expected, observed/expected ratio (o/e) 0.72, 90% interval 0.49 to 1.09. The upper end of that interval is the gene's LOEUF score, 1.09, which puts it in group 4 of 6, group 1 being the genes least tolerant of losing a copy. Missense variants: 510 observed, 547.72 expected, observed/expected ratio (o/e) 0.93, 90% interval 0.87 to 1. Synonymous variants: 256 observed, 259.92 expected, observed/expected ratio (o/e) 0.98, 90% interval 0.89 to 1.09.
Gene-disease validity (ClinGen):
ClinGen rates the evidence that CAVIN1 causes each of these diseases.
lipodystrophy (autosomal recessive): Definitive. A congenital or acquired disorder characterized by abnormal loss or redistribution of the adipose tissue in the body.
Homologues: Orthologues: chimpanzee CAVIN1 (99% identical), macaque CAVIN1 (99% identical), rat Cavin1 (94% identical), dog CAVIN1 (94% identical), mouse Cavin1 (93% identical), pig CAVIN1 (93% identical), guinea pig CAVIN1 (84% identical), tropical clawed frog cavin1 (68% identical), zebrafish cavin1b (59% identical), zebrafish cavin1a (47% identical). Paralogues in human: CAVIN2 (34% identical), CAVIN4 (25% identical), CAVIN3 (18% identical).
Diseases named in the same sentence as CAVIN1 in open-access papers:
CAVIN1 is named in the same sentence as 122 diseases in open-access papers, as found by Europe PMC text mining. Sharing a sentence is not in itself a finding about the gene and the disease. The quoted sentences say what the papers report.
prostate carcinoma (39 papers, 2011 to 2025). A carcinoma that arises from epithelial cells of the prostate gland. "For instance, the upregulation of caveolae-associated protein 1 (CAVIN1) enhances lipid storage, activates inflammatory pathways, and promotes invasion in prostate cancer stromal cells." (PMID 40566856, 2025). "Loss of PTRF/cavin-1 expression in prostate cancer has been related with progression, and it has been demonstrated that its expression decreases the migration of PTRF/cavin-1-deficient prostate cancer cells." (PMID 22461895, 2012). "Overall, this data suggest that changes in the plasma membrane involving loss of caveolae and PTRF/cavin-1 expression occur during prostate cancer progression." (PMID 22229094, 2011). "Also, TMB was found to be lower in prostate cancer cases with ICC-associated RESs in CAVIN1 or VWA8 or higher in prostate cancer cases with thymoma." (PMID 36969056, 2023). "Orthotopic implantation of the prostate-cancer cells with the stromal cells showed that CAVIN1 knockdown markedly increased the primary tumor lipid content and M2 macrophage infiltration and increased distant metastasis." (PMID 35158857, 2022). "Cavin-1 is highly expressed in proliferative tissues and ones rich in caveolae such as prostate cancer cells, rhabdomyosarcoma, endothelial cells, etc.." (PMID 35513070, 2022). "Cavin-1 was reported to enhance resistance to anticancer treatment in colorectal cancer but reduce the drug resistance in prostate cancer cells." (PMID 35722492, 2022). "The expression pattern CAV1+/CAVIN1‐ is replicated in the non‐caveolar PC3 (aggressive prostate cancer) cell line." (PMID 33931969, 2021). "Cavin1 emerges as a protein which, when exogenously expressed in prostate cancer cells, attenuates their aggressiveness 43-45." (PMID 32550897, 2020). "To identify signatures for caveolae, we compared PC3 prostate cancer cells that lack caveolae with PC3 cells transfected with the CAVIN1 adaptor required for caveolae formation." (PMID 31285524, 2019). "We previously reported that expression of PTRF/cavin-1 in prostate cancer PC3 cells reduced transmigration, via a decrease in MMP-9 production independent from de novo caveola formation." (PMID 22912783, 2012). "In agreement with a role for PTRF/cavin-1 in reducing cell migration, chemotaxis to serum was increased in three PTRF/cavin-1 down-regulated prostate cancer DU145 clones, compared to three clones stably transfected with scrambled shRNA." (PMID 22912783, 2012). "We have previously reported that exogenous expression of PTRF/cavin-1 in the prostate cancer cell line PC3, which expresses abundant caveolin-1 but lacks PTRF/cavin-1, significantly reduced transmigration on collagen-coated polycarbonate filters." (PMID 22912783, 2012). "In contrast to PTRF/cavin-1 of which expression levels decreased, the expression levels of Cav-1 and -2 increased in prostate cancer tissue." (PMID 22229094, 2011). "However, ectopic Cavin-1 overexpression inhibits tumor growth and metastasis due to antiangiogenesis- and antilymphangiogenesis-regulating functions as is reported in prostate cancer." (PMID 35722492, 2022). "To determine if CAVIN1 directly influences hnRNPK localisation or acts by neutralizing non‐caveolar CAV1, we ectopically expressed CAV1 in two cell lines that naturally lack CAV1 and CAVIN1, namely the androgen‐sensitive prostate cancer cell line LNCaP, and human embryonic kidney HEK293 cells." (PMID 33931969, 2021). "We developed a computational pipeline and applied it to analyzing 3D point clouds of SMLM localizations (event lists) of the caveolar coat protein, caveolin-1 (Cav1), in prostate cancer cells differentially expressing CAVIN1 (also known as PTRF), that is also required for caveolae formation." (PMID 29899348, 2018).
prostate carcinoma (continued). "Our recent studies showed that Cavin-1 expression in prostate cancer cells that express endogenous CAV1-modulated secretion pathways and cholesterol distribution, with decreased levels of cholesterol and impaired recruitment of actin to the detergent resistant membranes." (PMID 24714042, 2014). "Indeed, the protein was first identified as a nuclear polymerase and transcript release factor and in prostate cancer cells cavin-1 was found to act independently of caveolae." (PMID 24658465, 2014). "CAVIN1 expression is decreased during prostate-cancer progression and is strongly correlated with that of CAV1 in prostate-cancer cells and tumors." (PMID 35158857, 2022). "Polymerase I and transcript release factor (PTRF) is also known as cavin-1, and its down-regulation has been shown to promote the progression of prostate cancer, breast cancer, and glioblastoma." (PMID 35070996, 2021). "In prostate cancer, non‐caveolar caveolin‐1 (CAV1) promotes metastasis, while CAVIN1 attenuates CAV1‐induced metastasis." (PMID 33931969, 2021). "Next we made use of prostate cancer PC3 cells expressing abundant endogenous caveolin-1, and exogenous PTRF/cavin-1-GFP." (PMID 22912783, 2012). "PTRF/cavin-1 expression levels were significantly reduced in both LNCaP and PC3 cells and in prostate cancer tissue." (PMID 22229094, 2011). "The second information is the enhancement of prostate cancer cell migration and invasion that was observed in stromal cells lacking CAVIN1, leading to a poor outcome in patients." (PMID 36430209, 2022). "While these proteins are co‐expressed in healthy human cells, advanced prostate cancer cells express CAV1 without CAVIN1, leading to aberrant pro‐metastatic non‐caveolar CAV1 domains." (PMID 33931969, 2021). "A previous study demonstrated that Cavin1 expression in the prostate cancer cell line, PC3, did not alter EV secretion or distribution, but reduced EV internalization and EV-mediated osteoclastogenesis, probably via altering cargo recruitment." (PMID 32550897, 2020). "Hence our data support caveolar-dependent and caveolar-independent localization of caveolin-1 and PTRF/cavin-1 at discrete locations during transmigration in two different cell models: NIH3T3 fibroblasts and metastastic prostate cancer cells (PC3)." (PMID 22912783, 2012). "These claims were further substantiated by studies in Cav1-positive PC3 prostate cancer cells lacking cavin-1 and hence devoid of caveolae in which Cav1 siRNA knockdown, specifically eliminating scaffolds, reduces downstream Rho signaling, focal adhesion signaling and cell migration." (PMID 38526159, 2024). "PC3 is a metastatic prostate cancer cell line that expresses abundant levels of tyrosine phosphorylated Cav1 (pCav1) but lacks cell surface caveolae due to the absence of polymerase 1 and transcript release factor (PTRF)/cavin-1, required together with Cav1 for caveolae formation." (PMID 25942420, 2015).
lipodystrophy (24 papers, 2010 to 2025). "The MENA cohort included 10 patients who were diagnosed with CGL4, a rare lipodystrophy subtype caused by variants in the CAVIN1 gene that was first documented in 2002." (PMID 38481246, 2024). "Human mutations in Cav1 have been described that cause lipodystrophy and also in Cavin1 that lead to a similar phenotype." (PMID 36980283, 2023). "It has been reported that Cavin1 deficiency causes lipodystrophy in both humans and mice by affecting lipid metabolism." (PMID 33042738, 2020). "In humans, homozygous mutations in the PTRF/Cavin-1 gene have been reported to cause muscular dystrophy with lipodystrophy." (PMID 27612189, 2016). "PTRF/cavin-1 mutations were recently reported in patients with lipodystrophy and muscular dystrophy, correlating with perturbations in caveola function and further supporting a physiological role of PTRF/cavin-1 in caveolae." (PMID 22912783, 2012). "We know that loss of Cavin1 causes lipodystrophy and muscular dystrophy in humans." (PMID 33591275, 2021). "In CGL cells, there is a sign of combined lipodystrophy-related genes with a pattern of downregulation of CAVIN1 and FOS." (PMID 38755198, 2024). "Accumulation of rBMAs in the proximal tibia is dependent on expression of the gene cavin-1 lipodystrophy (Ptrf)." (PMID 37569635, 2023). "In addition, lipodystrophy-related genes were modulated: CAVIN1 (downregulated in infected AGPAT2mut vs. WT) and FOS (downregulated in AGPAT2mut and BSCL2mut vs. WT)." (PMID 38755198, 2024). "As Cavin1 is expressed in muscle and non-muscle tissues, Cavin1 mutations in humans cause lipodystrophies associated with myopathy, long-QT syndrome, and fatal cardiac arrhythmias, and Cavin4 mutations are linked to cardiac disease." (PMID 36980283, 2023). "Lipodystrophies have also been noted in humans and animals lacking either cavin-1 or caveolin-1 and the association of cavin-3 with cavin-1 and caveolin-1 combined with the dependence of cavin-3 protein on cavin-1 and caveolin-1 suggests that these lipodystrophies are caused by a common mechanism." (PMID 24069528, 2013).
breast carcinoma (21 papers, 2012 to 2025). "We also found an upregulation of CAVIN1 (caveolae associated protein 1) in HIV-positive breast cancer samples." (PMID 33194615, 2020). "Cavin-1 expression is significantly downregulated in breast cancer cell lines and breast cancer tissues and is closely related to its promoter methylation." (PMID 37828916, 2023). "Cavin-1 inhibits Cav-1-induced cell membrane tubule formation, and its specific role in breast cancer remains controversial." (PMID 37828916, 2023). "The downregulation of CAVIN1 reduced the amount of lipid rafts on the surface of the adriamycin-resistant breast-cancer cells and reduced the drug-resistant phenotype, suggesting the importance of CAVIN1 in mediating drug resistance via the lipid rafts." (PMID 35158857, 2022). "The expression of CAVIN1 is upregulated in an adriamycin-resistant breast-cancer cell line along with the expression of P-gp, CAV1, and CAVIN2." (PMID 35158857, 2022). "Any deleterious variant appearing in CAVIN1 will likely contribute to lower CAVINI expression and loss of stromal cell function, suggesting a role in breast cancer genesis and tumor development." (PMID 35589867, 2022). "Both CAVIN1 and CAVIN2 were significantly downregulated in breast cancer tissues and were associated with prognosis of patients." (PMID 34513683, 2021). "In silico analysis revealed upregulation of CAVIN1 in acquired lapatinib-resistant breast cancer." (PMID 35158857, 2022). "Cavin-1 and Cavin-3 were down-regulated in breast cancer with a low progression-free survival rate." (PMID 35722492, 2022). "Protein levels of all CAVs, CAVIN1, and CAVIN2 were associated with RFS of patients with Luminal A breast cancer, suggesting these caveolae-related genes can be potentially independent predictive factors of the prognosis of Luminal A breast cancer." (PMID 34513683, 2021). "As previous studies have proved that downregulation of CAVIN2 could cause reduction in CAVIN1 and CAV1 expression, the interdependency of these 3 molecules makes CAVIN2 as a prominent therapeutic target in breast cancer treatment." (PMID 34513683, 2021). "has reported cavin-1 was essential for drug resistance in breast cancer cell." (PMID 34513683, 2021). "Overexpression of caveolin-1 in a PTRF/cavin-1 null breast cancer cell line, SK-BR-3 was recently reported to elicit formation of long tubules that may mediate signaling events different from caveolae." (PMID 22912783, 2012). "The statistical results showed that CAV1, CAV2, CAV3, CAVIN1, and CAVIN2 were significantly less expressed in breast cancer tissues than in normal ones." (PMID 34513683, 2021). "The comprehensive analysis of cavins’ expressions and functions had provided evidences of significant roles of CAVIN1 and CAVIN2 in inhibiting breast cancer development." (PMID 34513683, 2021). "The results elucidated that the transcriptional levels of CAV1, CAV2, CAVIN1, CAVIN2, and CAVIN3 were significantly lower in breast cancer tissues than in normal samples." (PMID 34513683, 2021). "Our results elucidated that lower expression of CAV3, CAVIN1, and CAVIN2 significantly related to OS of patients with Luminal A breast cancer." (PMID 34513683, 2021). "Results elucidated that expression levels of CAV1, CAV2, CAVIN1, CAVIN2, and CAVIN3 were significantly lower in breast cancer tissues than in normal samples, while the expression level of CAVIN2 was correlated with advanced tumor stage." (PMID 34513683, 2021). "However, the specific role of Cavin-1 and Cav-1 in regulating IGF-IR in breast cancer is still controversial and needs further study." (PMID 37828916, 2023).
glioblastoma (18 papers, 2009 to 2025). The most malignant astrocytic tumor (WHO grade IV). "Polymerase I and transcript release factor (PTRF, cavin-1), which is a component of caveolae along with CAV1, is associated with chemoresistance in glioblastoma." (PMID 26646320, 2016). "Additionally, an emerging mediator of aberrant phospholipid metabolism in glioblastoma is polymerase I and transcript release factor (PTRF), also known as Cavin1." (PMID 34222022, 2021). "In glioblastoma, the scaffolding protein PTRF/Cavin-1 promotes NF-κB–dependent PD-L1 upregulation, contributing to immune escape." (PMID 41035656, 2025).